OGFRL1 (opioid growth factor receptor like 1)
Synonyms: dJ331H24.1
Tractability: Small molecule: a high-quality ligand is known. PROTAC: ubiquitination databases record sites on it; its protein half-life has been measured; a small molecule that binds it is known.
Target class: Membrane receptor
Gene: Protein-coding gene on chromosome 6 (71,288,811 to 71,309,059, forward strand). Ensembl gene ENSG00000119900.
Subcellular location (Human Protein Atlas): Golgi apparatus; Nucleoplasm
Gene Ontology:
Molecular function: opioid growth factor receptor activity; signaling receptor activity
Cellular component: membrane
Genetic constraint (gnomAD): Loss-of-function variants: 17 observed, 19.53 expected, observed/expected ratio (o/e) 0.87, 90% interval 0.6 to 1.31. The upper end of that interval is the gene's LOEUF score, 1.31, which puts it in group 5 of 6, group 1 being the genes least tolerant of losing a copy. Missense variants: 443 observed, 450.43 expected, observed/expected ratio (o/e) 0.98, 90% interval 0.91 to 1.06. Synonymous variants: 184 observed, 169.83 expected, observed/expected ratio (o/e) 1.08, 90% interval 0.96 to 1.22.
Homologues: Orthologues: chimpanzee OGFRL1 (98% identical), macaque OGFRL1 (89% identical), rabbit OGFRL1 (89% identical), dog OGFRL1 (89% identical), pig OGFRL1 (85% identical), mouse Ogfrl1 (81% identical), tropical clawed frog ogfrl1 (57% identical), rat Ogfrl1 (45% identical), zebrafish ogfrl1 (45% identical), guinea pig Ogfrl1 (20% identical). Paralogues in human: OGFR (33% identical).
Diseases named in the same sentence as OGFRL1 in open-access papers:
OGFRL1 is named in the same sentence as 4 diseases in open-access papers, as found by Europe PMC text mining. Sharing a sentence is not in itself a finding about the gene and the disease.
OGFRL1 shares sentences with these, for which no sentence is quoted: breast tumors (1 paper); cancer (1); multiple sclerosis (1); portal hypertension (1).